FST (follistatin)
Description:
Multifunctional regulatory protein whose primary function is to antagonize members of the transforming growth factor beta (TGF-beta) superfamily including activin, myostatin, GDF11 or bone morphogenetic proteins (BMPs). Mechanistically, binds to these ligands in the extracellular space, blocking their type II receptor-binding site to inhibit downstream signaling. Plays an essential role in muscle fiber formation and growth both by preventing the repressive effects of myostatin and through SMAD3/AKT/mTOR signaling independently of myostatin (By similarity). Also promotes neural differentiation by antagonizing the action BMP4 (By similarity). Acts as a specific inhibitor of the biosynthesis and secretion of pituitary follicle stimulating hormone (FSH) by sequestering activin A/INHBA. On the other hand, translocates into the nucleus where it down-regulates rRNA synthesis and ribosome biogenesis to maintain cellular energy homeostasis by binding to rDNA.
Synonyms: FS
Tractability: Antibody: UniProt places it where antibodies can reach, with high confidence; its Gene Ontology location is reachable by antibodies, with high confidence; UniProt predicts a signal peptide or a membrane-spanning region.
Gene: Protein-coding gene on chromosome 5 (53,480,210 to 53,487,134, forward strand). Ensembl gene ENSG00000134363.
Subcellular location: Secreted; Nucleus, nucleolus
Subcellular location (Human Protein Atlas): Vesicles; Predicted to be secreted
Pathways (Reactome):
Signal Transduction: Antagonism of Activin by Follistatin
Gene Ontology:
Molecular function: activin binding; activin receptor antagonist activity; protein binding; heparan sulfate proteoglycan binding
Biological process: hematopoietic progenitor cell differentiation; negative regulation of activin receptor signaling pathway; negative regulation of transcription by RNA polymerase II; positive regulation of hair follicle development; cell differentiation; regulation of BMP signaling pathway; cellular response to growth factor stimulus
Cellular component: extracellular region; cytoplasm; nucleolus; nucleus
Genetic constraint (gnomAD): Loss-of-function variants: 3 observed, 29.8 expected, observed/expected ratio (o/e) 0.1, 90% interval 0.045 to 0.26. The upper end of that interval is the gene's LOEUF score, 0.26, which puts it in group 1 of 6, group 1 being the genes least tolerant of losing a copy. Missense variants: 194 observed, 331.25 expected, observed/expected ratio (o/e) 0.59, 90% interval 0.52 to 0.66. Synonymous variants: 108 observed, 126.13 expected, observed/expected ratio (o/e) 0.86, 90% interval 0.73 to 1.
Homologues: Orthologues: chimpanzee FST (100% identical), macaque FST (99% identical), pig FST (98% identical), rat Fst (98% identical), mouse Fst (97% identical), guinea pig FST (96% identical), dog FST (90% identical), rabbit FST (79% identical), tropical clawed frog fst (78% identical), zebrafish fstb (66% identical), zebrafish fsta (66% identical). Paralogues in human: FSTL3 (33% identical), SPINK5 (25% identical), FSTL5 (20% identical), FSTL4 (19% identical), FSTL1 (13% identical), SPINK6 (7% identical).
Diseases named in the same sentence as FST in open-access papers:
FST is named in the same sentence as 187 diseases in open-access papers, as found by Europe PMC text mining. Sharing a sentence is not in itself a finding about the gene and the disease. The quoted sentences say what the papers report.
Obesity (27 papers, 2010 to 2026). Accumulation of substantial excess body fat. "According to Raeisi’s analysis and other studies, significant associations were found between follistatin levels and obesity." (PMID 39274528, 2024). "The results showed that follistatin suppressed obesity caused by a high-fat diet and increased insulin sensitivity, energy expenditure, and subcutaneous fat browning." (PMID 31365569, 2019). "Low expression levels of follistatin in adipose tissue from obese women have been linked with insulin resistance and hypertrophic obesity traits." (PMID 24763182, 2014). "Interestingly, in subjects with obesity, both muscle myostatin expression and circulating follistatin levels decreased after weight loss due to bariatric surgery, in parallel with the decrease in LBM and the increase in insulin sensitivity." (PMID 32316563, 2020). "Finally, this study showed that activins A or B or follistatin were significantly correlated with cardiovascular disease risk factors, such as obesity (BMI), smoking, and lipid profiles (HDL and triglyceride)." (PMID 23304117, 2012). "Using a comparative approach, we analyzed the effects of high-fat diet intake on myostatin and follistatin expression, spleen cell composition, and potential cytokine expression in high-fat diet induced obesity (HFDIO) resistant (SWR/J) and susceptible (C57BL/6) mice models." (PMID 20877574, 2010). "The aim of this study was to investigate if a relationship exists between myostatin, its antagonist follistatin, as well as irisin, with BMI, body-fat mass and various metabolic markers already in children and adolescents, particularly in a high-risk group suffering from severe obesity." (PMID 35631274, 2022). "We also showed that follistatin KO mice exhibited decreased exercise performance and altered skeletal homeostasis during obesity." (PMID 41272451, 2025). "Accordingly, the present study investigates the association between follistatin and PAI-1 levels in individuals with MASLD and obesity undergoing a controlled two-month dietary intervention." (PMID 40647228, 2025). "We analyzed the physiological effect of follistatin deletion in FAPs in response to exercise in obesity; the role of FAPs-derived follistatin in adaptation to exercise in NC and HFD-fed mice needs to be examined." (PMID 41272451, 2025). "This study aimed to investigate the emerging importance of follistatin as a potential biomarker for metabolically healthy and unhealthy obesity." (PMID 38793069, 2024). "This study aimed to investigate the potential of follistatin, a regulator of metabolic balance, as a biomarker to distinguish between metabolically healthy and unhealthy obesity." (PMID 38793069, 2024). "In this study, we explored a gene therapy approach to treat obesity in agouti mice using adeno-associated viruses (AAVs) carrying PRDM16, FoxP4, or Follistatin (FST) genes, which are known to promote the browning of white adipose tissue." (PMID 39596212, 2024). "Follistatin expression has been observed to change significantly in various metabolic disorders, such as obesity and type 2 diabetes mellitus (T2DM), suggesting a possible link between its dysregulation and metabolic health." (PMID 38793069, 2024). "Other genes therapies investigated for obesity include Follistatin (FST), Fibroblast growth factor 21 (FGF21), Adipose-derived mesenchymal stem cells (ADMSCs), and CRISPR-Cas9-based gene editing system." (PMID 37712012, 2023). "For instance, it has been shown in animals that follistatin induced by gene therapy mitigates systemic metabolic inflammation and post-traumatic arthritis in high-fat-diet-induced obesity." (PMID 35631274, 2022). "Patients with obesity-related to insulin resistance show an increase in the basal levels of follistatin." (PMID 33807959, 2021).
Obesity (continued). "In this review, we will discuss the evidence for the novel role of FST, MST and other related proteins in modulating TGF-β signaling and adipocyte browning to explore possible therapeutic avenues for the treatment of obesity and associated metabolic disorders." (PMID 33897620, 2021). "Apart from its impact on muscle mass, FST gene therapy has been proved to prevent HFD-induced obesity and completely normalize muscle glucose uptake in diet-induced insulin-resistant obese mice." (PMID 34491915, 2021). "One recent study reported the use of adeno-associated virus 9 (AAV9) as a vector to deliver the protein follistatin to improve muscle performance and mitigate the severity of osteoarthritis sequelae, including inflammation and obesity in mice." (PMID 33630874, 2021). "Weighted mean differences (WMDs) with corresponding 95% confidence intervals (CIs) were calculated to evaluate the strength of the association between the levels of resistin and follistatin with PCOS in the overall and stratified analysis by obesity status." (PMID 33740002, 2021). "Regarding myokines, the irisin level was lower (p < 0.001), while follistatin and myostatin levels were higher (p < 0.05), in patients with obesity compared with controls." (PMID 32316563, 2020). "Expectedly, like FGF21, patients with obesity-related insulin resistance present increased basal levels of follistatin, but its exercise-induced release by the liver is blunted." (PMID 32604889, 2020). "Myostatin and follistatin levels were slightly higher in women with obesity compared with normal-weight subjects." (PMID 32316563, 2020). "However, the mechanism via which FAPs-derived follistatin regulates exercise capacity and skeletal muscle homeostasis in obesity remains to be explored." (PMID 41272451, 2025). "To assess the impact of FAPs-specific deletion of follistatin under obesity-induced metabolic stress, first, we used 12-week and 24-week HFD-fed C57BL/6 J mice to examine whether the Fst expression alters with obesity." (PMID 41272451, 2025). "Therefore, to investigate the effect of obesity on skeletal muscle and glucose homeostasis of follistatin KO mice." (PMID 41272451, 2025). "Similarly, we observed a significant increase in follistatin concentration in the blood of women with overweight/obesity (BMI ≥ 25) compared to women with normal weight (BMI < 25.0)." (PMID 39274528, 2024). "Understanding the complex role of follistatin in metabolism may lead to the development of new therapies for obesity and T2DM." (PMID 38793069, 2024). "It has been reported that follistatin may hold potential in the treatment of obesity and related diseases, primarily due to its blocking of TGFβ ligands." (PMID 39274528, 2024). "In additional, studying tissue-specific expression patterns and exploring how follistatin affects metabolic parameters in different tissues may provide valuable insights into its role in obesity-related metabolic disorders." (PMID 38793069, 2024). "Myostatin positively and follistatin negatively correlated with age and pubertal (Tanner) stage, but none of the investigated myokines/hepatokines correlated with the BMI within this group with severe obesity." (PMID 35631274, 2022). "Since follistatin serum levels were elevated in PCOS patients in an obesity-independent manner, it might also have the potential as a non-invasive biomarker for PCOS." (PMID 36289764, 2022). "Analysis of muscle fiber type by gene expression analysis showed reduced expression of type II and mixed type muscle fiber markers in the TA of follistatin KO mice as compared to control mice which may reflect decreased fiber type maintenance under metabolic stress conditions like obesity." (PMID 41272451, 2025). "Follistatin is known for its important role in adipogenesis and metabolic regulation, and it has been hypothesized that it could serve as a biomarker to distinguish metabolic differences in individuals with obesity." (PMID 38793069, 2024).
Obesity (continued). "One reason for the lack of significant differences in the follistatin levels between metabolically healthy and unhealthy groups could be the inherent complexity and heterogeneity of metabolic disorders associated with obesity." (PMID 38793069, 2024). "Taken together, these data suggested that deletion of FAPs-derived follistatin enhanced MSTN/activin A/p-SMAD2/3 pathway, thereby accelerating skeletal muscle dysfunction in obesity." (PMID 41272451, 2025). "This study investigated the effects of three different interval resistance training (IRT) protocols and their effects on anthropometric indices, cardiometabolic markers, and levels of decorin, follistatin, myostatin, activin A, TGF-β1 in men with obesity." (PMID 35757424, 2022). "We determined the effects of IRT on the levels of select myokines (decorin, follistatin, myostatin, activin A, TGF-β) and cardiometabolic and anthropometric measures in males with obesity." (PMID 35757424, 2022). "Follistatin plays a protective role in mice by maintaining the metabolic health of skeletal muscles; it restores muscle function during HFD challenge, thereby reducing diet-induced obesity-related complications." (PMID 41272451, 2025). "Although it has been well documented that AST can eliminate the detrimental consequences triggered by obesity, there is scant evidence about its effects on changes in adipocytokines and myokines including TGF-β1, activin A, MST, FST, and DCN, which have cardinal roles during obesity." (PMID 39275173, 2024). "The results of this evaluation showed that the follistatin levels did not represent a significant difference between individuals with metabolically healthy obesity and those with metabolically unhealthy obesity." (PMID 38793069, 2024). "Girls with PCOS and without obesity showed similar serum follistatin concentrations as compared to age- and BMI-matched healthy girls, in contrast to previously reported data." (PMID 36843579, 2023). "In conclusion, this meta-analysis suggested that resistin and follistatin levels, independent of obesity status, were higher in women with PCOS compared with those in healthy controls." (PMID 33740002, 2021). "For follistatin and myostatin, differences with the reference values were accentuated in class III obesity, while for irisin the difference was accentuated in class I and II obesity." (PMID 32316563, 2020). "Collectively, these findings indicate that follistatin plays a protective role in mice by maintaining the metabolic health of skeletal muscles and restoring muscle function during HFD challenge, thereby reducing diet-induced obesity-related complications such as sarcopenia." (PMID 41272451, 2025). "Although follistatin may not serve as a discriminatory biomarker to distinguish between metabolically healthy and unhealthy obesity, our results emphasize the complexity of metabolic health in individuals who are obese." (PMID 38793069, 2024). "The increased resistin and follistatin levels in PCOS patients were independent of obesity status." (PMID 33740002, 2021). "Circulating levels of resistin and follistatin, independent of obesity status, are higher in women with PCOS compared with controls, showing that these adipokines may contribute to the pathology of PCOS." (PMID 33740002, 2021). "Concomitantly, resistance to release of exercise-inducible factors might also be involved, potentially elucidating, at least in part, why FGF21, follistatin, irisin, and METRNL are frequently increased in patients with obesity and T2DM, even in basal conditions." (PMID 32604889, 2020). "Together, these results implied that follistatin protects mice by preserving the metabolic health of skeletal muscles and maintaining skeletal muscle function during HFD intervention, which may lessen the consequences of diet-induced obesity, such as sarcopenia." (PMID 41272451, 2025).
Obesity (continued). "Although follistatin may not serve as a biomarker for identifying MHO and metabolically unhealthy obesity, understanding the underlying mechanisms that contribute to metabolic dysfunction could provide personalized strategies for managing obesity and preventing associated complications." (PMID 38793069, 2024). "Interestingly, while the follistatin levels showed no discriminatory power between metabolically healthy and unhealthy obesity, other biochemical markers, such as HDL cholesterol, triglycerides, C-peptide, and AST, showed significant differences between these two groups." (PMID 38793069, 2024). "Despite growing interest in metabolically healthy obesity (MHO) as a distinct phenotype, our results suggest that the follistatin levels do not differ significantly between metabolically healthy and unhealthy individuals." (PMID 38793069, 2024). "In line with our meta-analysis, previous studies have reported that circulating levels of follistatin are increased in PCOS independent of body mass index, suggesting that obesity is not the explanatory factor for the increased levels of follistatin among women with PCOS." (PMID 33740002, 2021).